AMACR (alpha-methylacyl-CoA racemase)
Diseases named in the same sentence as AMACR in open-access papers (continued):
Sharing a sentence is not in itself a finding about the gene and the disease.
prostate carcinoma (continued). "Alpha-methylacyl-CoA racemase (AMACR) is a mitochondrial and peroxisomal enzyme that is overexpressed in prostate cancer." (PMID 24130666, 2013). "PCSD1 xenograft tumors were characterized as PSA+, AR+, K5-, K14-, K8+, K18+, AMACR+, NKX3.1+, and TMPRSS2:ERG- human prostate cancer." (PMID 22035283, 2011). "The Kolmogorov-Smirnov tests for each of the 6 autoAb between prostate cancer and BPH/prostatitis groups were performed resulting in highly statistically significant differences between the two groups except for autoAb against AMACR." (PMID 21504557, 2011). "These were divided into three categories (40 cases of ASAP, 7 cases of prostate cancer with atypical foci and 3 cases of camouflaged morphology) and subjected to further analysis by immunohistochemistry with HMWCK and AMACR." (PMID 21176184, 2010). "Moreover, the CTLs exerted significant cytotoxic activity against AMACR-expressing prostate cancer cells in the context of HLA-A24, indicating that AMACR-derived peptides might be useful as prostate cancer vaccines for HLA-A24-positive/AMACR-expressing prostate cancer patients." (PMID 20003233, 2009). "The combination of GOLPH2 and AMACR showed expression of either marker in 99.2% of cancer cases, which advocates a combined use of AMACR and GOLPH2 as positive confirmative markers of prostate cancer." (PMID 18781151, 2008). "Such high-throughput analyses have recently identified new prostate cancer biomarkers, including, for example, HEPSIN, EZH2 and α-methyl-Co-racemase (AMACR)." (PMID 18781151, 2008). "Through the analysis of seven datasets (TCGA, GSE30521, GSE4602, GSE55945, GSE69223 GSE104131, and GSE200879), we identified two upregulated genes (AMACR and GCNT1) and seven downregulated genes (TGFB3, SRD5A2, PGM5, HOXD10, AOX1, HSPB6, and SNAI2) in prostate cancer compared to normal tissue." (PMID 38374143, 2024). "By using the combination of tumor cytomorphology and ICC showing the presence of tumor-like markers, either EMT markers (epithelial+/vim+), PSMA, AMACR, or TERT, we found 50 PGCC from 22 prostate cancer patients, with an average number of 2.3 (range from 1 to 10)." (PMID 37444476, 2023). "Besides PGCC, we also observed, in prostate cancers patients, the presence of smaller cells (<50 μm) expressing PSMA, AMACR, or other tumor markers, in variable amounts." (PMID 37444476, 2023). "AMACR, an isomerase with enriched expression in liver, renal, and prostate cancer, has been described in PCa fusions but not with itself; however, the fusion of ERG with itself is known to occur in PCa." (PMID 37349736, 2023). "Another outlier is AMACR, whose expression is elevated in prostate cancer compared to non-cancerous prostate samples." (PMID 36611998, 2022). "AMACR is a highly specific prostate cancer/ PIN marker with no expression observed in normal epithelial cells/ Benign or hyperplastic cells." (PMID 33884281, 2021). "In addition, this co-culture system with prostate stroma maintains differential expression of alpha-methylacyl-CoA racemase (AMACR), a well-established marker for prostate cancer, and increases the survival and passaging capacity of cancer derived-organoids." (PMID 33578886, 2021). "Finally, in some prostate cancer patients, gene fusions of SDK1 to AMACR (a-methylacyl-CoA racemase gene) and its transcript have been previously observed." (PMID 32982686, 2020). "AMACR was first identified as a gene upregulated in three of four expression array datasets from prostate cancer, but its importance as a cancer marker was not recognised until immunohistochemical studies of tissue sections were performed." (PMID 32708551, 2020). "In addition to AMACR, DBP and ACOX3, which are involved in β-oxidation, were highly expressed in prostate cancer tissue compared with matched normal tissues." (PMID 32674458, 2020).
prostate carcinoma (continued). "Thus, six biomarkers, including ERG, AMACR, SPINK1, NKX3.1, GOLM1, and AR predict higher aggressiveness of AAM than CaM prostate cancers; then, CaM had triple-negative (ERG-negative/ETS-negative/SPINK-1-negative) disease (51% vs. 35%)." (PMID 31366128, 2019). "The metabolic protein alpha-methylacyl-CoA racemase (AMACR) is significantly overexpressed in prostate cancer compared to the normal prostate and other non-malignant tissue." (PMID 30613352, 2018). "Alongside the microfluidic experiments, RT-qPCR was performed for each biopsy to assess the presence of prostate cancer cells and several prostate cancer biomarkers: androgen receptors (ARs), prostate-specific androgen (KLK3) and alpha-methyl-acyl-CoA racemase (AMACR)." (PMID 30279484, 2018). "All specimens were analyzed for AMACR expression and only one atrophic gland stained positive (data not shown) but did not represent prostate cancer pathologically." (PMID 23383057, 2013). "All recombinants were stained with alpha-methylacyl-CoA racemace (AMACR), a marker of prostate cancer and prostatic intraepithelial neoplasia and no recombinants had detectable expression of AMACR (data not shown)." (PMID 24405526, 2013). "Although, rs2278008 SNP of AMACR was reported previously with the significantly different genotype frequencies between hereditary prostate cancer groups and controls, this tendency was not shown when compared with a sporadic prostate cancer group." (PMID 24383053, 2013). "In a previous study sera from men with biopsy-proven prostate cancer and men without known prostate cancer have been screened for a humoral immune response to AMACR." (PMID 25586028, 2012). "Although the gene signatures of all forms of urogenital cancer/diseases are largely unknown, the six known prostate cancer genes of AGR2, AMACR, CRISP3, ERG, HPN, and PCA3 are at or below background, for example, in bladder cancer." (PMID 23029164, 2012). "While alpha-methylacyl-CoA-racemase (AMACR), also known as P504S, is a useful biomarker of prostate cancer, it is also expressed in some non-prostate cancers including urothelial cancers and therefore is not useful in making the distinction between PC and UC." (PMID 21777423, 2011). "Rarely high grade prostate carcinomas can express HMWCK and this is usually not a diagnostic problem as AMACR is positive in the malignant cells (as was in our cases) and morphology is diagnostic of malignancy." (PMID 21176184, 2010). "AMACR was first found overexpressed in prostate cancer but not in benign glands and is now an established diagnostic marker for prostate cancer." (PMID 19148275, 2009). "In addition to AMACR and p63, GOLPH2 antibodies will be helpful in the correct histological diagnosis of prostate cancer." (PMID 18781151, 2008). "The high rate of GOLPH2 protein overexpression, which is also seen in AMACR-negative prostate cancer cases, suggests its use as an additional ancillary positive tissue marker of prostate cancer." (PMID 18781151, 2008). "Some of these genes were already extensively studied in prostate cancer, mostly those upregulated in tumor tissue: SPINK1 (Top17, logFC 4.8), ETV4 (Top63, logFC 3.6), PCA3 (Top79, logFC 3.5), TDRD1 (Top86, logFC 3.4), AMACR (Top105, logFC 3.2), DLX1 (Top110, logFC 3.1), HOXC6 (Top268, logFC 2.3)." (PMID 31170942, 2019). "The gene expression pattern (up-regulated AMACR mRNA and down-regulated p63 mRNA) in LNCAP cells (normalized to benign RWPE-1 cells) represents the protein staining pattern (up-regulated AMACR and absent p63 protein) in primary prostate cancer tissue with high AMACR expression." (PMID 25514598, 2015). "We also observed that proteins involved in fatty acid oxidation, such as AMACR, ACOX-3 and DBP, were restricted to the tumour cells, which is consistent with the presence of a metabolic pathway different from glycolysis, and compatible with oxidative phosphorylation in prostate cancer cells." (PMID 24886074, 2014).
prostate carcinoma (continued). "The function of AMACR in prostate cancer has not been clarified yet." (PMID 20003233, 2009). "However, PSA and AMACR staining were still negative and ruled out prostate cancer." (PMID 41291370, 2025). "Along this line, we speculated that the AMACR-induced cell cycle progression might be operated by more diverse mechanisms, perhaps indirect and cell type-dependent, given the previously reported G2/M cell cycle arrest in AMACR-silenced LAPC-4 prostatic cancer cells." (PMID 25473890, 2014). "Differential expression analysis revealed genes that have been previously reported to be up regulated in prostate cancer, e.g. HPN and AMACR (data not shown)." (PMID 21912659, 2011). "In addition, candidate peptides from AMACR, p90 autoantigen, and LEDGF were screened using serum samples from prostate cancer patients and control samples from HD (data not shown)." (PMID 21504557, 2011).
prostate adenocarcinoma (23 papers, 2008 to 2025). "Previous studies found AMACR protein and mRNA tissue expression to be specific to PCa and therefore suggested AMACR as a highly sensitive diagnostic marker for prostate adenocarcinoma." (PMID 37634036, 2024). "Hematoxylin-eosin and alpha-methylacyl-CoA racemase stains were performed to identify regions of prostatic adenocarcinoma and potentially high-grade prostatic intraepithelial neoplasia." (PMID 37719014, 2023). "Recently, the downregulation of miR-26a was first found to link to the increased AMACR expression level in prostatic adenocarcinomas, and AMACR was further validated by functional assays to be a novel target of this tumor suppressive microRNA." (PMID 25473890, 2014). "The aim of this study was to investigate the expression patterns of AMACR and iNOS in prostate adenocarcinomas with different histopathologic grade." (PMID 24353588, 2013). "Of these, the most widely used is AMACR, which is expressed in 80% - 100% of prostatic adenocarcinomas." (PMID 22800084, 2012). "alpha-Methylacyl-CoA racemase (AMACR), an immunomarker for prostatic adenocarcinoma, has been shown to be expressed in a variety of other neoplasms." (PMID 18577240, 2008). "In contrast, areas of prostatic adenocarcinoma showed absent nuclear p63 staining due to loss of basal epithelial cells, together with the gain of brown granular cytoplasmic staining indicating expression of AMACR in malignant glands." (PMID 22800084, 2012). "AMACR and NKX3.1 were both positive for protein expression, which is expected with prostate adenocarcinoma." (PMID 40497995, 2025). "This case highlights the utility of these three immunostains (AMACR, p63 and CK903/34βE12) in the accurate diagnosis of adenosis of the prostate on needle biopsy, and avoiding its misinterpretation as prostate adenocarcinoma." (PMID 18700013, 2008). "The case herein presented highlights the utility of AMACR, p63 and CK903/34βE12 immunostaining in the accurate diagnosis of adenosis of the prostate, a benign mimicker of prostate adenocarcinoma." (PMID 18700013, 2008). "As expected, no AMACR was present in healthy prostate tissue, but intense staining was observed in prostate adenocarcinoma and metastatic lesions acquired from liver and lymph node." (PMID 30613352, 2018). "Prostate adenocarcinoma may be readily differentiated from bladder adenocarcinoma by virtue of its positivity for PSA and PSAP; other markers that help to confirm a prostate origin include Leu7 and AMACR." (PMID 27006847, 2016). "Additionally, while PSA negativity is atypical for prostate adenocarcinoma, the absence of GATA3, a marker of urothelial origin, along with the positive AMACR, supported a diagnosis of prostatic ductal adenocarcinoma." (PMID 40662003, 2025).
prostate tumor (11 papers, 2013 to 2025). "Additional analysis of prostate tumour specimens was focused on expression of AMACR–gene encoding an enzyme considered to be overexpressed in PC, yet with many contradictory data published, which occurred to be slightly lower in PEPCs than in tissue samples (0.376±0.048 compared with 0.556±0.028)." (PMID 27803125, 2016). "In prostate tumours, we found that both Siglec-7 and Siglec-9 ligands co-localised with α-methylacyl-CoA racemase (AMACR), suggesting that they are found in cancerous glands within the prostate." (PMID 38448753, 2024). "AMACR is far from being a lineage specific marker: prostatic tumor cells commonly express this AMACR, as well as adenocarcinomas arising from the liver, bladder, colon, ovary, breast." (PMID 38791935, 2024). "The last gene evaluated in this study codes the enzyme AMACR, which is overexpressedin prostate tumor tissue." (PMID 32484847, 2020). "The expression of AMACR, which converts the (R) form of phytanoyl-CoA to the (S) form for subsequent β-oxidation, was upregulated in prostate tumor tissues." (PMID 32674458, 2020). "We also showed that the AMACR and p63 protein staining pattern in prostate tumors and benign glands mirrors the mRNA expression pattern in LNCAP cells and RWPE-1 cells." (PMID 25514598, 2015). "We use of this technique to separate prostate tumor and benign cells in human prostate needle biopsies based on the expression levels of the tumor marker alpha-methylacyl-CoA racemase (AMACR)." (PMID 25514598, 2015). "Pristanic acid is formed during peroxisomal oxidation of phytanic acid, and is the direct substrate of α-Methyl-CoA-Racemase (AMACR)—an enzyme that is consistently overexpressed in prostate tumors relative to benign tissue." (PMID 25132681, 2014). "To test the specificity of our AMACR SmartFlare oligos in cell culture systems, we selected two cell lines with significantly different expression levels of AMACR: the prostate tumor cell line LNCAP (high AMACR expression) and the benign prostate cell line RWPE-1 (low AMACR expression)." (PMID 25514598, 2015). "Increased recurrence rates and low overall survival were observed in prostate tumor patients with erythroblast transformation-specific related gene (ERG) positivity and high AMACR expression." (PMID 32674458, 2020). "Compared to adjacent non-tumor tissue, AMACR is overexpressed in prostate tumors from AA men (log2fold change: 1.85, P < 0.001) and EA men (log2fold change: 2.70, P < 0.001)." (PMID 38566104, 2024). "No single cell analysis data regarding AMACR expression in living human prostate tumor cells are available for comparison." (PMID 25514598, 2015). "Unfortunately, prostate tumor cells from patients SP07 and LA08 could not be maintained to allow the analysis of the binding of the peptide and AMACR marker." (PMID 40733075, 2025).
papillary renal cell carcinoma (10 papers, 2013 to 2024). A rare subtype of renal cell carcinoma, arising from the renal tubular epithelium and showing a papillary growth pattern, which typically manifests with hematuria, flank pain, palpable abdominal mass or nonspecific symptoms, such as fatigue, weight loss or fever. "The tumour was positive for PAX8 and negative for TTF-1 indicating the renal origin of the tumour while positivity for AMACR & CK7 confirmed the diagnosis of papillary renal cell carcinoma." (PMID 38265103, 2024). "It is well known that AMACR is a positive marker in about 70% of papillary renal cell carcinomas, 71% of colorectal adenocarcinoma, and 77% of hepatocellular carcinomas." (PMID 37383161, 2023). "Similar immunohistochemical markers (CK7 and AMACR) have also been reported between papillary adenoma and papillary renal cell carcinoma." (PMID 35449090, 2022). "Papillary renal cell cancer is differentiated from other subtypes of renal cell cancer by using CK7 and AMACR immunohistochemical markers." (PMID 23402579, 2013). "Immunohistochemically, the tumor cells were positive for WT-1 and CD57 but negative for AMACR, which was helpful to exclude the possibility of papillary renal cell carcinoma." (PMID 24083046, 2013). "On the other hand, AMACR (Alpha-methylacyl-CoA racemase) is frequently positive in Xp11 translocation renal cell carcinomas, as well as in papillary renal cell carcinomas, but CK7 is typically negative in Xp11 translocation renal cell carcinomas and positive in papillary renal cell carcinomas." (PMID 31382581, 2019).
renal cell carcinoma (9 papers, 2009 to 2025). "Among the 35 MiT family translocation renal cell carcinomas tested, AMACR, instead, stained positive in 26 (74%), 19 (54%), and 18 cases (51%), regarding a 5%, 10%, and 20% cutoff respectively." (PMID 35980471, 2022). "Recently, it has been reported that AMACR is overexpressed in various tumor tissues, including renal cell cancer, hepatic cancer, colon cancer and lung cancer." (PMID 20003233, 2009). "On the other hand, no relevant statistical correlation was found with immunohistochemical expression of either CD10, AMACR, or CD13, in contrast with the data observed with TFE3-rearranged renal cell carcinomas." (PMID 35980471, 2022). "While AMACR is not useful in the differential diagnosis with TFE3-rearranged renal cell carcinomas, being positive in both tumors, such marker is usually under-expressed in TFEB-rearranged renal cell carcinomas." (PMID 35980471, 2022). "On immunohistochemistry, unlike renal cell carcinoma, glomus tumors are negative for epithelial markers and markers native to renal origin like PAX8 (paired box gene 8)/AMACR (alpha-methylaceyl CoA racemase)/CA IX (carbonic anhydrase IX)." (PMID 38449999, 2024). "However, in TFEB-rearranged renal cell carcinoma, CD10 and AMACR staining are not statistically correlated (p = 0.5 and p = 1 respectively)." (PMID 35980471, 2022).
clear cell carcinoma (8 papers, 2015 to 2025). "In the present study, we evaluated the diagnostic accuracy of AMACR as a potential immunohistochemical marker for clear cell carcinoma histotype." (PMID 37383161, 2023). "At the endometrium, the immunoreactivity of AMACR in clear cell carcinoma, endometrioid carcinoma, and serous carcinoma was 36%, 24%, and 0%, respectively." (PMID 37383161, 2023). "Clear cell carcinomas frequently expressed AMACR, HNF1B, and Napsin A (83.3%, 66.7%, and 66.7%, respectively)." (PMID 33986807, 2021). "AMACR may be a highly specific immunohistochemical marker for the distinction of serous and clear cell carcinoma." (PMID 37383161, 2023). "Similarly, the diagnostic value of AMACR (α-methylacyl-coenzyme-A racemase or p504s), which has been reported to be frequently positive in clear cell carcinoma, requires further study 64,65." (PMID 30550483, 2019). "In females, this differential diagnosis is expanded to clear-cell carcinoma of the female genital (napsin A, WT1 and PR positive) tract and in males with clear-cell renal-type prostatic acinar adenocarcinoma (AMACR- and NKX3.1-positive)." (PMID 41562801, 2025). "Immunohistochemically, clear cell carcinomas are typically positive for HNF-1B, and often for napsin A and/or Alpha methyacyl CoA racemase (AMACR)." (PMID 33670088, 2021).
prostatic intraepithelial neoplasia (7 papers, 2008 to 2023). "High-grade prostatic intraepithelial neoplasia cells found within PCa sections demonstrated low (32%; 6 out of 19) to moderate (21%; 4 out of 19) levels of expression for AMACR, with a small percentage staining high (10%; 2 out of 19)." (PMID 18648369, 2008).